APOBEC3C (apolipoprotein B mRNA editing enzyme catalytic subunit 3C)
Description:
DNA deaminase (cytidine deaminase) which acts as an inhibitor of retrovirus replication and retrotransposon mobility via deaminase-dependent and -independent mechanisms. After the penetration of retroviral nucleocapsids into target cells of infection and the initiation of reverse transcription, it can induce the conversion of cytosine to uracil in the minus-sense single-strand viral DNA, leading to G-to-A hypermutations in the subsequent plus-strand viral DNA. The resultant detrimental levels of mutations in the proviral genome, along with a deamination-independent mechanism that works prior to the proviral integration, together exert efficient antiretroviral effects in infected target cells. Selectively targets single-stranded DNA and does not deaminate double-stranded DNA or single- or double-stranded RNA. Exhibits antiviral activity against simian immunodeficiency virus (SIV), hepatitis B virus (HBV), herpes simplex virus 1 (HHV-1) and Epstein-Barr virus (EBV) and may inhibit the mobility of LTR and non-LTR retrotransposons. May also play a role in the epigenetic regulation of gene expression through the process of active DNA demethylation.
Synonyms: A3C; APOBEC1L; PBI; bK150C2.3; ARDC2; ARDC4; ARP5
Tractability: PROTAC: ubiquitination databases record sites on it; its protein half-life has been measured.
Target class: Enzyme; Hydrolase
Gene: Protein-coding gene on chromosome 22 (39,014,224 to 39,020,352, forward strand). Ensembl gene ENSG00000244509.
Subcellular location: Nucleus; Cytoplasm
Subcellular location (Human Protein Atlas): Intermediate filaments
Pathways (Reactome):
Metabolism of RNA: Formation of the Editosome; mRNA Editing: C to U Conversion
Gene Ontology:
Molecular function: protein binding; RNA binding; cytidine deaminase activity; hydrolase activity; zinc ion binding
Biological process: clearance of foreign intracellular DNA; negative regulation of viral genome replication; positive regulation of gene expression via chromosomal CpG island demethylation; transposable element silencing; cytidine to uridine editing; defense response to virus; DNA cytosine deamination; negative regulation of single stranded viral RNA replication via double stranded DNA intermediate; defense response to symbiont
Cellular component: cytoplasm; nucleus; P-body
Genetic constraint (gnomAD): Loss-of-function variants: 15 observed, 21.88 expected, observed/expected ratio (o/e) 0.69, 90% interval 0.46 to 1.06. The upper end of that interval is the gene's LOEUF score, 1.06, which puts it in group 4 of 6, group 1 being the genes least tolerant of losing a copy. Missense variants: 244 observed, 251.14 expected, observed/expected ratio (o/e) 0.97, 90% interval 0.87 to 1.08. Synonymous variants: 98 observed, 92.78 expected, observed/expected ratio (o/e) 1.06, 90% interval 0.9 to 1.25.
Homologues: Paralogues in human: APOBEC3F (77% identical), APOBEC3D (76% identical), APOBEC3B (42% identical), AICDA (41% identical), APOBEC3G (41% identical), APOBEC3A (38% identical), APOBEC3H (35% identical), APOBEC2 (31% identical), APOBEC1 (25% identical).
Diseases named in the same sentence as APOBEC3C in open-access papers:
APOBEC3C is named in the same sentence as 39 diseases in open-access papers, as found by Europe PMC text mining. Sharing a sentence is not in itself a finding about the gene and the disease. The quoted sentences say what the papers report.
breast carcinoma (6 papers, 2013 to 2026). "Meanwhile, a similar trend was observed for TNM stage, with higher APOBEC3B and lower APOBEC3C mRNA level associated with advanced breast cancer stage." (PMID 26682542, 2015). "Some investigations have shown that the expression of APOBEC3C played a positive role in the invasiveness and prognosis of breast cancer, hepatocellular carcinoma, and prostate cancer." (PMID 32431729, 2020). "At present, there are few studies about APOBEC3C in breast cancer, and some studies have found that it should play a positive role in the invasiveness and prognosis of hepatocellular carcinoma." (PMID 30881302, 2019). "Consistent with human cell line data, Ets1 expression was negatively correlated with Dnmt3a and Dnmt3b in normal specimens, while Ets1 level is positively correlated with Apobec3c in human breast cancer specimens." (PMID 30467308, 2018). "In conclusion, our integrated analyses suggested that APOBEC3B and APOBEC3C expression patterns were correlated with ER status and clinical outcome, providing an additional implication that these two genes may contribute to mutation profile and clinical outcome in breast cancer subtypes." (PMID 26682542, 2015). "Along with high expression levels of APOBEC3C gene in ER− breast cancer cells, it is possible that both APOBEC3B and APOBEC3C retain DNA cytosine deaminase activity in breast cancer." (PMID 26682542, 2015). "Although no functional assays are performed in this study, several lines of evidence support the possible functionality of the APOBEC3C protein in breast cancer." (PMID 26682542, 2015). "For example, we observed that the elevated expression levels of APOBEC3C but lowered expression levels of APOBEC3B in breast cancer patients have better clinical outcomes." (PMID 26682542, 2015). "Meanwhile, many studies have strongly indicated the enhanced activity of LINE-1 retrotransposons in human cancers induces genome instability, DNA damage, and genetic variation, further implying the potentially functional roles of APOBEC3C in breast cancer." (PMID 26682542, 2015). "However, none of the deaminases analysed to date (AID, APOBEC1, APOBEC3C, 3DE, 3F and 3G) has been shown to exhibit a preference that accords with the breast cancer kataegic mutations." (PMID 23599896, 2013). "The transcriptome data from both breast cancer cell lines and tumor specimens reveal that the APOBEC3B and APOBEC3C genes show significant differences at the transcription levels between ER+ and ER− breast tumors." (PMID 26682542, 2015). "For example, APOBEC3B and APOBEC3C show low DNA methylation levels (median methylation ratio ≤20 %) in both HMEC and ER− breast cancer cells, although a slight increase in ER− cancer cells." (PMID 26682542, 2015). "The survival analysis suggested that DCAF13, EZR, MRPL13, APOBEC3C, and EIF4E3 might have a prognostic value for breast cancer." (PMID 30881302, 2019).
glioma (6 papers, 2012 to 2025). A benign or malignant brain and spinal cord tumor that arises from glial cells (astrocytes, oligodendrocytes, ependymal cells). "APOBEC3C is associated with various immune‐infiltrating cell types in the glioma TME." (PMID 40704619, 2025). "Furthermore, it was confirmed that APOBEC3C is specifically associated with infiltrating immune cells in gliomas, suggesting that APOBEC3C plays a vital role in the immune evasion mechanism of gliomas." (PMID 40704619, 2025). "The results of this study suggest that high expression of APOBEC3C is associated with poor prognosis in glioma and may affect immune regulation." (PMID 40704619, 2025). "We found that APOBEC3C is involved in immune responses and closely related to inflammatory activity in the glioma TME." (PMID 40704619, 2025). "Gliomas with APOBEC3C expression presented significant correlations with various immune markers in different immune cells and T‐cell subsets." (PMID 40704619, 2025). "In line with previous research, knocking down APOBEC3C was capable of inhibiting the malignant progression of gliomas via the NF‐κB signaling pathway." (PMID 40704619, 2025). "The results of in‐vitro experiments also attested to the efficacy of APOBEC3C as a potential therapeutic target for glioma." (PMID 40704619, 2025). "APOBEC3C was enriched in malignant glioma subtypes and was a potential biomarker for mesenchymal subtypes in glioma patients." (PMID 40704619, 2025). "To evaluate the specificity of APOBEC3C expression in glioma mesenchymal subtypes, we utilized receiver operating characteristic (ROC) curves." (PMID 40704619, 2025). "Although the results of this study enhance our understanding of the relationship between APOBEC3C and gliomas, several limitations remain." (PMID 40704619, 2025). "Based on the CGGA and TCGA databases, we conducted Kaplan–Meier (K–M) and Cox proportional hazards model analyses to assess the prognostic significance of APOBEC3C in gliomas." (PMID 40704619, 2025). "To validate the effect of APOBEC3C on the malignant progression of gliomas, we analyzed the correlation between APOBEC3C and the EMT process as well as its representative genes." (PMID 40704619, 2025). "Bioinformatics methods were applied to reveal the possible mechanisms of APOBEC3C‐mediated malignant progression of gliomas." (PMID 40704619, 2025). "APOBEC3C is preferentially enriched in the mesenchymal subtype with a poor prognosis, indicating its potential as a mesenchymal biomarker for gliomas." (PMID 40704619, 2025). "Collectively, these findings suggest that gliomas with more aggressive phenotypes are characterized by elevated APOBEC3C expression levels." (PMID 40704619, 2025). "Since the mesenchymal subtype of GBM is more aggressive than other subtypes, these findings further confirm that APOBEC3C is positively correlated with the malignancy level of gliomas." (PMID 40704619, 2025). "To validate the relationship between high levels of APOBEC genes and reduced survival in an independent dataset, we looked at the overexpression of APOBEC3G and APOBEC3C in gliomas in the REMBRANDT dataset." (PMID 22829908, 2012). "Knocking down APOBEC3C can inhibit the invasion and migration abilities of glioma cells." (PMID 40704619, 2025). "Future research should focus on elucidating the role of APOBEC3C in glioma through integrated single‐cell sequencing and multiomics analysis to uncover its interactions with immune cells in the TME, followed by experimental validation of its impact on immunotherapy efficacy." (PMID 40704619, 2025). "So, these data imply that APOBEC3C may play a significant role in glioma immune and inflammatory responses, making it an important immune target." (PMID 40704619, 2025). "This study examines the prognosis and therapeutic potential of APOBEC3C in glioma." (PMID 40704619, 2025). "APOBEC3C is involved in regulating macrophage polarization in gliomas." (PMID 40704619, 2025).
glioma (continued). "Finally, the mechanism of action of APOBEC3C in gliomas requires further exploration for a deeper understanding." (PMID 40704619, 2025). "Moreover, western blot, transwell, and cell‐scratch assays were used to explore the potential mechanisms of APOBEC3C‐mediated glioma invasion and migration." (PMID 40704619, 2025). "In addition, APOBEC3C can regulate the activation of the NF‐κB signaling pathway, which is expected to be a target for improving immunotherapy in glioma patients." (PMID 40704619, 2025). "These checkpoints were strongly positively correlated with APOBEC3C, indicating that APOBEC3C may suppress immune responses against gliomas." (PMID 40704619, 2025). "Additionally, APOBEC3C is a potential independent prognostic factor for glioma, and inhibition of APOBEC3C expression can suppress the EMT process in glioma cells through the NF‐κB signaling pathway." (PMID 40704619, 2025). "In gliomas, APOBEC3C was positively correlated with markers of monocytes, TAMs, and M2 macrophages." (PMID 40704619, 2025). "Recent research reports have also demonstrated the potential value of APOBEC3C in glioma patients." (PMID 40704619, 2025). "In this study, five prognosis-related differentially expressed immune-related genes (PR-DE-IRGs) (CCNA2, HMGB2, CASP3, APOBEC3C, and BMP2) highly associated with glioma were identified for a prognostic model through weighted gene co-expression network analysis, univariate Cox and lasso regression." (PMID 35601497, 2022). "Furthermore, transwell experiments demonstrated that knocking down APOBEC3C using siRNA technology under in‐vitro conditions could significantly inhibit the migration and invasion abilities of glioma cells." (PMID 40704619, 2025). "Moreover, APOBEC3C was highly expressed in malignant glioma subtypes and could function as a biomarker for mesenchymal glioma subtypes." (PMID 40704619, 2025). "However, the role of APOBEC3C in glioma is still poorly understood." (PMID 40704619, 2025). "Similarly, cell‐scratch experiments showed that knocking down APOBEC3C could inhibit the horizontal migration ability of glioma cells U87‐MG." (PMID 40704619, 2025). "Our study found a correlation between APOBEC3C expression and the remodeling of the tumor microenvironment (TME) in glioma." (PMID 40704619, 2025). "Therefore, APOBEC3C may play an immunomodulatory role in gliomas." (PMID 40704619, 2025). "The mRNA expression of APOBEC3C, FCGRT, GNG5, and SP100 was elevated in glioma, whereas the expression of ADAP2, ALOX5AP, and LRRC25 was low." (PMID 32431729, 2020). "High expression of APOBEC3C may lead to an increase in macrophages and dendritic cells while decreasing CD8+ T cells, thus contributing to the poor cumulative survival rate of glioma patients." (PMID 40704619, 2025). "Analysis of the CGGA database revealed that APOBEC3C expression was positively correlated with glioma WHO grade, elevated in samples lacking 1p/19q codeletion, and higher in IDH wild‐type patients." (PMID 40704619, 2025).
viral infection (6 papers, 2016 to 2023). "We validated this prediction by comparing changes in protein expression during WT and ΔVif virus infections, and demonstrated that as with APOBEC3C degradation, Vif was necessary for depletion of the PP2A regulatory subunits PPP2R5A-E." (PMID 27690223, 2016).
asthma (4 papers, 2020 to 2023). "In another ICS response study in admixed children from GALAII and SAGE cohorts with asthma, rs5995653 SNP related to apolipoprotein B mRNA-editing catalytic polypeptide 3 (APOBEC3)B and APOBEC3C genes was associated with a protective effect against asthma exacerbations." (PMID 37228580, 2023). "APOBEC3B and APOBEC3C, genes that have not been previously associated with asthma, encode subunits of a cytidine deaminase, a protein with an RNA editing function that has an important role in the immune response to several viruses by restricting their replication." (PMID 32326339, 2020).
COVID-19 (3 papers, 2022 to 2024). A disease caused by infection with severe acute respiratory syndrome coronavirus 2. "We found a high expression of APOBEC3A, APOBEC3B, APOBEC3C, APOBEC3D, APOBEC3F, APOBEC3G and APOBEC3H in the classical, intermediate monocytes and NK cells of the COVID-19 patients compared to the healthy or recovered individuals." (PMID 36532041, 2022).
gastric cancer (3 papers, 2019 to 2026). A primary or metastatic malignant neoplasm involving the stomach. "For example, the expression APOBEC3C was associated with increased APOBEC-mutational signature in cervical and head and neck cancers, while its expression was associated with decreased APOBEC-mutational signature in stomach cancer." (PMID 31533728, 2019).
prostate carcinoma (3 papers, 2020 to 2026). A carcinoma that arises from epithelial cells of the prostate gland. "The dysregulation of HERV activation restriction genes has also been found in other cancers, such as the overexpression of TET1, TET3, and APOBEC3B but downregulation of APOBEC3C, 3G, 3D, 3H, and C2 in prostate cancer, and different cancers may involve different activation restriction genes." (PMID 37509325, 2023).
malignant glioma (2 papers, 2012 to 2025). A grade III or grade IV glioma arising from the central nervous system. "Interestingly, in the REMBRANDT dataset high expression of APOBEC3C was also prognostic in other malignant gliomas including anaplastic astrocytoma and anaplastic oligodendroglioma (p = 0.02 and p = 0.03, respectively)." (PMID 22829908, 2012).
anaplastic astrocytoma (1 paper, 2012). "High APOBEC3C expression remained significant in anaplastic astrocytoma and showed a trend toward significance in anaplastic oligodendroglioma even when the model was adjusted for age (p = 0.02 and p = 0.07, respectively)." (PMID 22829908, 2012).
cervical cancer (1 paper, 2020). A primary or metastatic malignant neoplasm involving the cervix. "Therefore, we also integrated the APOBEC family (APOBEC1 APOBEC3A, APOBEC3B, APOBEC3C, APOBEC3D, APOBEC3F, APOBEC3G, and APOBEC3H) mRNA expression of 176 core-set cervical carcinoma samples for multiplatform integrative analyses." (PMID 32211324, 2020).
clear cell renal cell carcinoma (1 paper, 2025). "The authors discovered that expression of the RNA‐binding protein APOBEC3C (A3C) promotes clear cell renal cell carcinoma (ccRCC) growth by amplifying nuclear factor‐kappa B (NF‐κB) activity." (PMID 39183666, 2025). "This study demonstrates that the RNA‐binding protein APOBEC3C (A3C) is frequently upregulated in clear cell renal cell carcinoma (ccRCC)." (PMID 39183666, 2025).
colon tumors (1 paper, 2021). "However, our data show that certain APOBECs (e.g. APOBEC3A, APOBEC3C, APOBEC3D, etc.)are highly expressed in CYT-high colon tumors, providing evidence of their involvement in them." (PMID 34316699, 2021).
Hepatitis (1 paper, 2024). Inflammation of the liver. "Studies have shown that APOBEC3C is associated with infections of RNA viruses such as hepatitis and HIV." (PMID 38693480, 2024).
HIV-1 infection (1 paper, 2005). The type species of lentivirus and the etiologic agent of acquired immunodeficiency syndrome (AIDS). "Likewise, Yu and colleagues have recently reported that human APOBEC3B and APOBEC3C can inhibit SIV but not HIV-1 infection of human cells." (PMID 15998449, 2005).
juvenile idiopathic arthritis (1 paper, 2023). Juvenile idiopathic arthritis (JIA) is the term used to describe a group of inflammatory articular disorders of unknown cause that begin before the age of 16 and last over 6 weeks. "A gene-set analysis indicated that IgG glycosylation (TAB1, MGAT3, and CACNA1I) and Response to methotrexate in juvenile idiopathic arthritis (CACNA1I and APOBEC3C) may engage common underlying genetic vulnerabilities." (PMID 37029179, 2023).
lentivirus infection (1 paper, 2016). Virus diseases caused by the Lentivirus genus. "Thus, the high expression of APOBEC3C in HIV target cells and the antagonism of APOBEC3C by HIV-1 Vif are consistent with the hypothesis that APOBEC3C may have an overlooked role in combating lentivirus infection." (PMID 27732658, 2016).
lung carcinoma (1 paper, 2015). "According to these results, we suggested that rs139293 was probably associated with reduced lung cancer risk by destroying the structure of APOBEC3H and regulating the expression of APOBEC3C and APOBEC3H." (PMID 26459911, 2015).
metastatic melanoma (1 paper, 2021). A melanoma that has spread from its primary site to another anatomic site. "In contrast, increased expression was associated with good clinical outcomes in metastatic melanoma except for APOBEC3B and APOBEC3C." (PMID 34638749, 2021).
ovarian carcinoma (1 paper, 2016). A malignant neoplasm originating from the surface ovarian epithelium. "The resulting two main clusters for ovarian cancer cell lines accentuate the expression differences for APOBEC3B, APOBEC3C, and APOBEC3G as well as of ID2 and ID3." (PMID 27527602, 2016).
papilloma (1 paper, 2013). A benign epithelial neoplasm that projects above the surrounding epithelial surface and consists of villous or arborescent outgrowths of fibrovascular stroma. "The implication of APOBEC3A fits with data from others revealing that enforced expression of APOBEC3A (as well as APOBEC3C and 3H) can lead to mutation of human papilloma viral DNA as well as of transfected plasmid DNA." (PMID 23599896, 2013).